Y_RNA (Y RNA )
Gene: Miscellaneous RNA gene on chromosome 17 (62,661,621 to 62,661,725, reverse strand). Ensembl gene ENSG00000207382.
Homologues: Orthologues: chimpanzee Y_RNA (100% identical). Paralogues in human: RNY1P1 (81% identical), Y_RNA (81% identical), RNY1P5 (80% identical), Y_RNA (80% identical), RNY1 (79% identical), Y_RNA (79% identical), Y_RNA (78% identical), RNY1P11 (77% identical), Y_RNA (77% identical), RNY1P8 (76% identical), Y_RNA (76% identical), RNY1P15 (75% identical), and 92 more.